KIR2DS4 (killer cell immunoglobulin like receptor, two Ig domains and short cytoplasmic tail 4 (gene/pseudogene))
Description:
Receptor on natural killer (NK) cells for HLA-C alleles. Does not inhibit the activity of NK cells.
Synonyms: NKAT-8; CD158i; KKA3; NKAT8; cl-39; KIR-2DS4; KIR1D; KIR412
Gene: Protein-coding gene on chromosome 19 (54,832,676 to 54,848,569, forward strand). Ensembl gene ENSG00000221957.
Subcellular location: Cell membrane
Genetic constraint (gnomAD): Missense variants: 356 observed, 280.24 expected, observed/expected ratio (o/e) 1.27, 90% interval 1.16 to 1.39. Synonymous variants: 110 observed, 107.93 expected, observed/expected ratio (o/e) 1.02, 90% interval 0.87 to 1.19.
Homologues: Orthologues: mouse Kir3dl2 (25% identical), mouse Kir3dl1 (25% identical), rat Kir3dl1 (24% identical), tropical clawed frog xilr1 (12% identical). Paralogues in human: KIR2DL1 (52% identical), KIR2DL3 (52% identical), KIR3DL2 (50% identical), KIR3DL1 (47% identical), KIR3DL3 (44% identical), LILRB1 (29% identical), LILRB2 (28% identical), LILRA2 (26% identical), LILRA1 (25% identical), LILRB5 (24% identical), LILRA4 (24% identical), LILRB3 (24% identical), and 13 more.
Diseases named in the same sentence as KIR2DS4 in open-access papers:
KIR2DS4 is named in the same sentence as 46 diseases in open-access papers, as found by Europe PMC text mining. Sharing a sentence is not in itself a finding about the gene and the disease. The quoted sentences say what the papers report.
COVID-19 (11 papers, 2021 to 2025). A disease caused by infection with severe acute respiratory syndrome coronavirus 2. "The study illustrated that KIR2DS4 is uniquely linked to severe cases of COVID-19, whereas both KIR2DS4 and KIR3DL1 are associated with mild, moderate, and severe manifestations of the disease." (PMID 40391199, 2025). "The COVID-19 patients with severe disease had a greater prevalence of deleted variant of KIR2DS4 compared to the mild group (p = 0.03, CI = 1.032–2.429 ، OR = 1.58)." (PMID 38943065, 2024). "A comparison of AA genotype carriers in the two groups of patients and controls in terms of KIR2DS4 variants revealed that the frequency of the del/del genotype was significantly higher in severely ill COVID-19 patients." (PMID 38943065, 2024). "A recent report found that peptides bound to HLA-C*05:01 are recognized by one of the activating KIR (KIR2DS4) and this allele was significantly associated with the risk of death from COVID-19." (PMID 34344463, 2021). "KIR2DS4 has also been associated with COVID-19 in other populations." (PMID 40244151, 2025). "The KIR2DL1/HLA-C2 complex has been linked to increased disease severity, and the frequency of KIR2DS4 and KIR3DL1 genes has been associated with a risk of severe COVID-19, suggesting a significant role of these genetic markers in antiviral immunity." (PMID 40244151, 2025). "Another haplotype A (AA180) was found in COVID-19 and HIV cohorts at the same frequency (2%); all of them have deleted variants of KIR2DS4." (PMID 36555106, 2022). "Two studies on COVID-19 patients have shown that the KIR2DS4 gene is associated with the risk of severe COVID-19, although KIR2DS4 variants were not identified." (PMID 38943065, 2024). "In a recent study of 424 COVID-19 positive patients (392 Saudi, 32 non-Saudi), the KIR2DS4 gene was associated with the highest risk of severe COVID-19 infection (OR 8.48, p= 0.0084) followed by KIR3DL1 (OR 7.61, p=0.0192)." (PMID 35874712, 2022). "Complementary to this scenario of NK cell activating receptors being important in mitigating symptom severity as previously reported, we found that the KIR2DS4 gene, which belongs to the KIR receptors gene family, was correlated with mild progression of COVID-19." (PMID 39470726, 2024). "Higher frequencies for KIR2DS4 in severe COVID-19 patients and KIR3DS1+HLA-B*15:01+ in mild/moderate cases of COVID-19 than in control in Spanish indicate a potentially detrimental effect of activating KIR in COVID-19." (PMID 35273641, 2022).
Autoimmunity (3 papers, 2012 to 2019). The occurrence of an immune reaction against the organism's own cells or tissues. "In this setting, KIR2DS4 polymorphism can provoke the immune response as it can modulate autoimmunity." (PMID 23028591, 2012). "KIR genes consist of two haplotypes; The “A” haplotype contains inhibitory genes and one activating gene (KIR2DS4) with protective effect against autoimmunities." (PMID 30696403, 2019). "As NK cells are potently activated by KIR2DS4, overstimulation could have negative consequences, such as inflammation and autoimmunity." (PMID 31138701, 2019).
Cirrhosis (3 papers, 2011 to 2017). A chronic disorder of the liver in which liver tissue becomes scarred and is partially replaced by regenerative nodules and fibrotic tissue resulting in loss of liver function. "Interestingly, homozygosity for KIR2DS4-FL, the frequency of which was increased in patients with CHCV infections, was associated with the presence of cirrhosis." (PMID 29354127, 2017). "Furthermore, homozygosity for the KIR2DS4-FL genotype was also associated with progression to cirrhosis (33 vs. 19% in the non-cirrhotic group, p = 0.03, OR: 2.1)." (PMID 29354127, 2017).
HIV-1 infection (3 papers, 2014 to 2025). The type species of lentivirus and the etiologic agent of acquired immunodeficiency syndrome (AIDS). "In general, our new findings here are highly consistent with earlier epidemiologic evidence of association between functional, full-length KIR2DS4 alleles and the likelihood of transmitting HIV-1 infection by chronically infected individuals." (PMID 24901871, 2014). "In other words, the relationship of full-length KIR2DS4 with unfavorable outcomes during chronic HIV-1 infection could be caused by other genes that are inherited as one unit (haplotype-A)." (PMID 24901871, 2014). "A study conducted in Burkina Faso reported that the KIR2DL2, KIR2DS2, KIR2DS3, KIR2DS4, and KIR3DS1 genes were associated with HIV-1 infection, while the KIR3DL1 gene was associated with protection against HIV-1 infection." (PMID 40244151, 2025). "Compared to 60 HIV-1- controls, HIV-1 infection was associated with significant changes within the NK cell receptor repertoire, including reduced percentages of NK cells expressing NKG2A, CD8, and KIR2DS4." (PMID 35911762, 2022). "KIR2DS4 has been associated with high viral loads and promotion of HIV-1 pathogenesis in chronic HIV-1 infection, probably through excessive NK cell activation." (PMID 35911762, 2022). "KIR2DS4+ and KIR2DS4− NK cells derived from subjects with chronic HIV-1 infection showed differential CD107a, IFN-γ and MIP-1β expression profiles after stimulation with HLA-deficient K562 cells." (PMID 24901871, 2014). "Associations of full-length KIR2DS4 gene with longitudinal viral load (VL) and CD4+ T-cell (CD4) count in 207 youth with chronic (seroprevalent) HIV-1 infection." (PMID 24901871, 2014). "Depending on KIR2DS4 expression (presence or absence) on cell surface, NK cells from 43 individuals with untreated, chronic HIV-1 infection often differed in functional properties, including degranulation and secretion of IFN-γ and MIP-1β." (PMID 24901871, 2014). "The positive correlation between KIR2DS4 expression and HIV-1 VL may well suggest that changes in microenvironments (e.g., severe defects in lymphoid tissues and the gastrointestinal tract) following HIV-1 infection contribute to the observed functional properties of KIR2DS4-positive NK cells." (PMID 24901871, 2014).
melanoma (3 papers, 2011 to 2015). A malignant, usually aggressive tumor composed of atypical, neoplastic melanocytes. "In this context, it has been described that KIR2DS4 is able to interact with a protein expressed on melanoma cell lines and on a primary melanoma." (PMID 25961063, 2015). "Notably, KIR2DS4 is able to interact with a non-HLA class-I protein expressed on melanoma cell lines and on a primary melanoma." (PMID 24678311, 2014).
rheumatoid arthritis (3 papers, 2014 to 2025). A chronic, systemic autoimmune disorder characterized by inflammation in the synovial membranes and articular surfaces. "Moreover, HLA-Cw4 and KIR2DS4 were associated with rheumatoid arthritis." (PMID 33015197, 2020). "Rheumatoid arthritis (RA): A KIR2DS4-full gene located at the Tel section showed strong links to elevated RA risks in comparison to KIR2DL5A as the inhibitory gene of the Cen area which demonstrated protective qualities." (PMID 40486331, 2025). "This study shows that the presence of the full-length KIR2DS4 gene reduces the probability that patients affected by rheumatoid arthritis will respond to methotrexate therapy." (PMID 25069714, 2014).
Diabetes (2 papers, 2022 to 2025). "Collectively, these results suggest that KIR3DL1 and KIR2DS4 as well as KIR2DL3 can be associated with diabetes and hypertension, respectively, among people living and aging with HIV." (PMID 35071606, 2022).
glomerulonephritis (2 papers, 2012 to 2016). A renal disorder characterized by damage in the glomeruli. "Our results suggest a protective role of KIR2DS5 in graft rejection and an association of KIR2DS4 with kidney rejection, particularly in recipients with glomerulonephritis." (PMID 23028591, 2012). "Individuals from the glomerulonephritis group possessing both variants of KIR2DS4 and perfect HLA-B,-DR matching had about 15 times higher chance of rejection than analogous persons from the non-glomerulonephritis group (both panels)." (PMID 23028591, 2012). "Similarly, the presence of both types of KIR2DS4 alleles gave highest risk of kidney graft rejection, particularly in recipients with glomerulonephritis as a cause of kidney failure." (PMID 26206121, 2016). "In contrast, in recipients with glomerulonephritis, HLA compatibility seemed to be much less important for graft rejection than the presence of KIR2DS4 gene." (PMID 23028591, 2012). "In contrast, in recipient group with glomerulonephritis, HLA incompatibility seemed to be much less important than KIR2DS4 for graft rejection." (PMID 23028591, 2012). "Namely, in the non-glomerulonephritis group, HLA-B,-DR matching seemed to be much more important for acute graft rejection than the presence or absence of KIR2DS4 gene variants." (PMID 23028591, 2012). "In our study, we observed a strong effect of KIR2DS4 variants in patients with glomerulonephritis, where HLA-B,-DR mismatch exerted much weaker influence on the graft fate, whereas in recipients without glomerulonephritis the effect of HLA-mismatch was predominant." (PMID 23028591, 2012). "The lack of strong association of graft rejection with HLA-B,-DR mismatching in recipients with glomerulonephritis could not have been observed in earlier studies done without stratification for the presence or absence of KIR2DS4 gene." (PMID 23028591, 2012).
acute coronary syndrome (1 paper, 2012). Signs and symptoms related to acute ischemia of the myocardium secondary to coronary artery disease. "It is interesting in this context that KIR2DS4 molecule was expressed on remarkable proportion of CD4+CD28− T cell clones isolated from an acute coronary syndrome patient." (PMID 23028591, 2012).
Encephalopathy (1 paper, 2023). Encephalopathy is a term that means brain disease, damage, or malfunction. "Except for KIR2DS4+, KIR2DS3+, and the inhibitor gene KIR2DL1+, which were found to be increased in patients with encephalopathy, it was found that the frequency of most KIR genes (activators and inhibitors) decreased in patients with encephalopathy who died from MF." (PMID 37046435, 2023).
endometriosis (1 paper, 2010). The growth of functional endometrial tissue in anatomic sites outside the uterine body. "On the other hand, only KIR2DS5 gene was (negatively) associated with susceptibility to endometriosis, and KIR2DS4 deletion variant was less frequent in peritoneal form of this disease (our unpublished data)." (PMID 20865034, 2010).
hepatitis B virus infection (1 paper, 2016). A viral infection caused by the hepatitis B virus. "Nevertheless, in hepatitis B virus infection in the Chinese, both full-length and deleted alleles of KIR2DS4 were associated with hepatocellular carcinoma; the presence of both of them was required for maximal effect." (PMID 26206121, 2016).
influenza (1 paper, 2014). An acute viral infection of the respiratory tract, occurring in isolated cases, in epidemics, or in pandemics; it is caused by serologically different strains of viruses (influenzaviruses) designated A, B, and C, has a 3-day incubation period, and usually lasts for 3 to 10 days. "NK cell response related genes such as CD247, KIR2DL4, KIR3DL1, KIR3DL3 and KLRB1 were down-regulated only in moderate and severe patients while genes such as KIR2DL1, KIR2DS4 and KIR3DL2 were down-regulated in all three groups of influenza patients." (PMID 25365328, 2014).
meningioma (1 paper, 2023). A generally slow growing tumor attached to the dura mater. "Six antigens were exclusively found in the immunopeptidome of WHO grade I meningiomas (CAPN14, KIR2DS4, TMM44, ECD, CD86, and RFWD3), whereas WHO grade I and III meningiomas showed only one antigen in common (KLC2)." (PMID 37368072, 2023).
myelogenous leukemia (1 paper, 2019). "KIR genotype frequency differed significantly between myelogenous leukemia patients and healthy controls for KIR2DL5A (17.6% vs. 47.7%, p=0.02), KIR3DS1 (17.6% vs. 47.6%, p=0.02), and KIR2DS4*001 (36.6% vs. 20.2%, p=0.017)." (PMID 31337191, 2019).
nephritis (1 paper, 2023). Inflammation of renal tissue. "Perhaps the most intriguing finding within the study of IgAV skin is that the KIR transcripts detected with the KIR Activating Subgroup 1 probe (KIR3DS1, KIR2DS1, KIR2DS2, and KIR2DS4) are the most highly differentially depressed skin transcripts in patients with IgAV who develop nephritis." (PMID 37036681, 2023).
preeclampsia (1 paper, 2019). Preeclampsia is a hypertensive disorder of pregnancy that is characterized by new-onset hypertension with proteinuria presenting after 20 weeks of gestation, and depending on mild or severe forms may initially present with severe headache, visual disturbances, and hyperreflexia. "Carrying KIR2DS4-fl is associated with protection from preeclampsia and glioblastoma, and with higher viral loads and faster progression to AIDS in HIV infection (19, 24, –26)." (PMID 31138701, 2019). "Given that KIR2DS4 protects from preeclampsia, a disorder of insufficient blood supply to the fetus, it is possible that a high frequency of KIR2DS4 and HLA-C*05:01 had a negative effect in those populations because of too high a birth weight." (PMID 31138701, 2019).
viral infections (1 paper, 2021). "Apart from bacterial infections, KIR2DS4 may be associated with the outcome of viral infections." (PMID 34220799, 2021).
infection (6 papers, 2017 to 2025). The state of being infected such as from the introduction of a foreign agent such as serum, vaccine, antigenic substance or organism. "Among Africans, KIR2DS4 confers a significant risk of infection, while KIR2DL2, KIR2DL5, and KIR2DS3 provide protection." (PMID 40244151, 2025). "However, the typing of different KIR2DS4 alleles revealed an increased frequency of the functional KIR2DS4 alleles (KIR2DS4-FL) in patients with CHCV infections (0.52 vs. 0.42 in healthy controls, p = 0.02)." (PMID 29354127, 2017). "Specifically, a positive association was observed between the risk of infection and the following genes: the inhibitory genes KIR2DL3 and KIR3DL1, along with the activating genes KIR2DS1 and KIR2DS4." (PMID 40244151, 2025). "Genetic variants of KIR2DS4, KIR2DS1, KIR2DL1, and HLA-C increase susceptibility to infection." (PMID 40244151, 2025). "An additional scenario is that KIR2DS4+ NK cells could be activated upon interaction with APCs that present RecA epitopes on HLA-C to produce IFN-γ early during infection, and to facilitate a T helper 1 response necessary to clear the bacterial infection." (PMID 31138701, 2019).
tumor (5 papers, 2020 to 2024). "Whereas no ligand for KIR2DS2 were found on all tumor cells, C*05:01 and C*02:02 alleles serving as ligands for KIR2DS4 were present in HT18584 and HT18816 primary GBM cells, respectively." (PMID 35628668, 2022). "Interestingly, both inhibitory KIR (KIR2DL1, KIR2DL3 and KIR3DL1) and activating KIR (KIR2DS1 and KIR2DS4) were reduced in expression when effectors were exposed to tumor in the presence of TriKE." (PMID 32961861, 2020).
bacterial infection (2 papers, 2019 to 2021). "Disease association studies of KIR2DS4 and HLA-C*05:01 with outcome of bacterial infections will be needed to test this idea further." (PMID 31138701, 2019). "However, a recent study showed that KIR2DS4 exhibits peptide selective binding to HLA-C which might be significant for the NK cell response to human bacterial infections." (PMID 34220799, 2021). "In the context of bacterial infections, the stimulation of IFN-γ production by KIR2DS4+ NK cells is likely to contribute to clearance of bacterial pathogens." (PMID 31138701, 2019).
cancer (1 paper, 2019). A tumor composed of atypical neoplastic, often pleomorphic cells that invade other tissues. "Therefore individuals with haplotype A being homozygous for the deleted KIR2DS4 will carry only inhibiting KIRs which has been associated with a protective role against some types of cancer such as HNSCC33." (PMID 30796344, 2019).
KIR2DS4 also shares sentences with these, for which no sentence is quoted: metastatic colorectal cancer (3 papers); acute graft versus host disease (1); brucellosis (1); chronic hepatitis (1); gastric cancer (1); gastroenteritis (1); head and neck squamous cell carcinoma (1); Hepatitis (1); hepatocellular carcinoma (1); Hypertension (1); kidney diseases (1); kidney failure (1); leukemia (1); liver cirrhosis (1); neuroblastoma (1); non-small cell lung carcinoma (1); ovarian carcinoma (1); Peptic ulcer (1); pregnancy disorder (1); psoriasis (1); Salmonella Infections (1); sexually transmitted infection (1); syphilis (1); type 1 diabetes (1).